ENSG00000199857
Synonyms: LOC124900891
Gene: Small nucleolar RNA gene on chromosome 4 (76,402,076 to 76,402,146, forward strand). Ensembl gene ENSG00000199857.
Gene Ontology:
Biological process: RNA processing
Cellular component: nucleolus
Homologues: Orthologues: rat LOC120096381 (72% identical). Paralogues in human: SNORD50B (63% identical).